MPO (myeloperoxidase)
Diseases named in the same sentence as MPO in open-access papers (continued):
Sharing a sentence is not in itself a finding about the gene and the disease.
heart failure (continued). "Below, we briefly introduce the biochemical properties and physiological roles of MPO and provide an overview of the enzyme’s role in the development of atherosclerotic CAD, followed by a focus on MPO’s role in I/RI during MI and heart failure." (PMID 39061857, 2024). "The serum level of myeloperoxidase is known to be useful in predicting short and long-term prognosis following ACS, MI and cardiac failure." (PMID 35815198, 2022). "The extra risk of accelerated CVD may be a result of increased myeloperoxidase and CRP protein level, together with decreased vitamin D. Increased NT-proBNP may be evidence of early impairment of the myocardial muscle and a marker of early development of heart failure." (PMID 36012972, 2022). "Myeloperoxidase (MPO) is released during polymorphonuclear neutrophil (PMN) degranulation, and mediates dysregulation of vascular tone in heart failure." (PMID 25867530, 2015). "Based on the data, the important variables associated with the occurrence of NOAF were selected: age, CAD, heart failure, WBC, neutrophils, neutrophil percentage, CRP, PCT, TNF-α, MPO, HOCl, CR, TNI, NT-proBNP, LDL-c, SOFA score, APACHE II score, LVEF, and LVFS." (PMID 39030470, 2024). "Furthermore, a specific MPO blocker (AZD4831) with anti-inflammatory and -fibrotic properties has been clinically applied in patients with heart failure with preserved ejection fraction." (PMID 37280612, 2023). "At the same time, high circulating levels of MPO in serum, plasma, or white blood cells could be used as a predictor of major cardiac adverse events in healthy people and in patients with CHD or heart failure." (PMID 33317561, 2020). "Also, MPO was proposed as a biomarker for predicting future cardiovascular events such as ACIC in the setting of trastuzumab exposure and heart failure." (PMID 28493232, 2017). "In addition, recent results from a clinical phase 2a study (Safety and Tolerability Study of AZD4831 in Patients With Heart Failure, SATELLITE) revealed therapy with the MPO inhibitor AZD4831 to be well tolerated and safe in heart failure patients with preserved ejection fraction." (PMID 40252642, 2025). "Interestingly, mean MPO levels were significantly higher in patients with heart failure, but only in the non-diabetic group." (PMID 36463116, 2022). "Mean MPO levels were significantly elevated in non-diabetic patients with heart failure." (PMID 36463116, 2022). "Considering EAT activity might be affected by age, gender, heart failure, and atrial size, we performed subgroup analysis to adjust for gender, age, AF type, BNP, LA, and RA size, and identified that Gal-3 and MPO remain independently correlated with enhanced EAT activity." (PMID 34712708, 2021). "MPO levels may predict the presence of heart failure, independent of other markers, such as age and BNP." (PMID 34073616, 2021). "Furthermore, MPO inhibition may also be beneficial in other cardiacconditions characterized by impaired diastolic function such as LVH due to arterialhypertension and heart failure with preserved ejection function." (PMID 33705529, 2022). "Thus, MPO may evolve as an early marker of heart failure that does not simply reflect ventricular dysfunction, but points to humoral and structural alterations that predispose to heart failure." (PMID 25296036, 2014).
systemic lupus erythematosus (63 papers, 2005 to 2025). An autoimmune multi-organ disease typically associated with vasculopathy and autoantibody production. "This reduction was evident through diminished staining for extracellular DNA (Sytox Orange) and NET-associated proteins (MPO), presenting a notable contrast to the heightened levels observed in lupus, Dexamethasone drug and W treated counterparts." (PMID 39544931, 2024). "The prominent features were mainly MPO-associated LN, and the pathological types were mainly proliferative lupus, especially type IV-G." (PMID 32228220, 2020). "NET components such as dsDNA, histones, MPO, vimentin, and enolase have been associated to systemic pathology linked with disease entities such as small vessel vasculitis, systemic lupus erythematosus (SLE), disseminated intravascular coagulation, preeclampsia, and rheumatoid arthritis." (PMID 36839481, 2023). "However, additional studies are required to assess whether MPO inhibitors could suppress the production of pathogenic auto-antibodies similar to that observed with PAD inhibitors in models of lupus, collagen-induced arthritis, and colitis." (PMID 36421487, 2022). "In a lupus mouse model 6-gingerol administration significantly reduced serum levels of anti-dsDNA, cell-free DNA and also MPO-DNA complexes, the latter of which serves as a marker of NET formation." (PMID 39007134, 2024). "The tissue-specific accumulation of MPO and Sytox Orange was systematically assessed in the liver, kidneys, and heart of mice across various treatment groups, lupus, Dexamethasone drug, DW, IW, and W treated mice along with healthy control mice." (PMID 39544931, 2024). "Lupus mice displayed heightened levels of Sytox Orange and MPO, indicating an enhanced presence of extracellular DNA and NET-associated proteins." (PMID 39544931, 2024). "Serologies were positive for ANCA, myeloperoxidase (MPO), immunoglobulin G (IgG), anti-double-stranded deoxyribonucleic acid (DS-DNA) IgG, and lupus anticoagulant panel." (PMID 39574988, 2024). "NETs were detected in renal glomeruli using co-staining of MPO, neutrophil elastase, and citrullinated histone H3 for these mice Together, these observations suggest an increased level of NETs in lupus pathogenesis." (PMID 35686129, 2022). "The underlying diseases were idiopathic ON (n = 6), Bechet’s disease (n = 5), NMO (n = 3), systemic lupus erythematosus (SLE) (n = 2), sarcoidosis (n = 1), relapsing polychondritis (n = 1), and myeloperoxidase-anti-neutrophil cytoplasmic antibody-associated vasculitis (n = 1)." (PMID 32796717, 2020). "A proportion of lupus-prone MRL/lprfas mice develop MPO-ANCA that bind to MPO on the neutrophil surface." (PMID 32373109, 2020). "The fact that NETs containing MPO as well as intact neutrophils are present in the dermis and dermal blood vessels of cutaneous lupus lesions suggests that enhanced NET formation occurs in vivo in affected organs of SLE patients." (PMID 32355207, 2020). "The relative number of MPO-positive leukocytes in the lupus group were increased compared to the control group, but this difference was not statistically significant (p > 0.05)." (PMID 27648095, 2016). "IgM anti-MPO antibody-secreting lymphocytes are present in the peripheral repertoire of lupus-prone mice but rarely differentiate into IgG-producing cells." (PMID 16207324, 2005). "Inhibition of NETs formation or MPO effectively alleviates TREM2-mediated lupus progression." (PMID 41276972, 2025). "In systemic lupus erythematosus (SLE), excessive NETosis results in the release of NET-associated molecules (DNA, histones, MPO, and others) that serve as autoantigens, promoting autoantibody production and complement activation, thereby contributing centrally to disease pathogenesis." (PMID 41465350, 2025). "Notably, lupus mice exhibited a significant and pronounced increase in both Sytox Orange and MPO compared to the healthy control group." (PMID 39544931, 2024).
systemic lupus erythematosus (continued). "Furthermore, impaired PON1 activity and elevated MPO levels were reported in systemic lupus erythematosus (SLE)." (PMID 36671490, 2023). "The most frequently occurring keyword was a neutrophil extracellular trap (1608), followed by inflammation, NETosis, extracellular trap, infection, DNA, myeloperoxidase, immunity, innate immunity, systemic lupus erythematosus, NADPH oxidase, elastase, cell death, apoptosis, and mitochondrial DNA." (PMID 37233403, 2023). "In the current studies we directly test the hypothesis that anti-DNA and anti-MPO autoreactive B cells recruited to the lungs of cSiO2-exposed female lupus-prone BXSB mice are a source of autoantibodies." (PMID 35983030, 2022). "While NETosis is induced by various stimuli including IFN-α, our data might indicate that TREM-1 potentiates NET release in lupus patients with high serum MPO-DNA levels as observed in sepsis." (PMID 36319843, 2022). "Considering that serum MPO-DNA complex levels were decreased in lupus patients with a high titer of anti-dsDNA antibody, it is also possible that anti-dsDNA antibodies physiologically deplete circulating NETs and thus do not allow activation of macrophages by NET per se." (PMID 36319843, 2022). "Due to the non-detectable renal MPO and NE in lupus mice at 120 h post-I/R, renal injury was not directly caused by NETs but perhaps the enhanced glomerular IC deposition." (PMID 34248948, 2021). "The P-ANCA-positive APS patients had major vascular events, including pulmonary emboli, and thrombocytopenia, while the anti-MPO/elastase patient had lupus-like phenotype with mouth ulcers, alopecia, Raynaud’s phenomenon, pulmonary emboli, leukopenia and thrombocytopenia." (PMID 34440897, 2021). "Indeed, MPO-ANCAs have been reported in systemic lupus erythematosus (SLE; 9.3%), rheumatoid arthritis (RA; 4–18%), Sjögren’s syndrome (SS; <3%) and systemic sclerosis (SScl; <2.4%)." (PMID 34440897, 2021). "In addition, disordered regulation of NETosis has been suggested to be involved in the pathogenesis of autoimmune diseases, including systemic lupus erythematosus (SLE) and anti-thyroid drug propylthiouracil (PTU)-induced MPO-ANCA-associated vasculitis." (PMID 27375623, 2016). "Injection of the NET-loaded mDCs into mice resulted in anti-MPO autoantibodies and an autoimmune phenotype including glomerulitis, although the kidney histopathology was in some ways more reminiscent of lupus lesions than the typical pauci-immune disease of SVV." (PMID 23248629, 2012). "Villanueva and colleagues showed an enhanced expression of proteins linked to neutrophil antimicrobial activity in systemic lupus erythematosus (SLE) [e.g., myeloperoxidase (MPO), neutrophil elastase (ELANE), alpha defensin 4 (DEFA4)]." (PMID 38596677, 2024). "As such, Syk inhibitor attenuated NETosis (serum dsDNA, MPO, and glomerular NETs) and glomerular apoptosis in Fcgr2b-/- mice at 24 h post renal-I/R affected to decreased glomerular Ig deposition and attenuated lupus activity (anti-dsDNA, proteinuria and Scr) after 120 h post renal-I/R." (PMID 34248948, 2021). "Indeed, PAD4 inhibitor decreased NETs (serum dsDNA, serum MPO, and glomerular NETs) at 24 h post-renal I/R and attenuated lupus characteristics (anti-dsDNA, proteinuria and Scr) at 120 h post-renal I/R supporting an impact of NETs formation on anti-dsDNA production and lupus exacerbation." (PMID 34248948, 2021). "Interestingly, the anti-MPO positive lupus patient had no renal involvement, while anti-lactoferrin specificity was linked to the most severe clinical phenotype as opposed to double anti-MPO/lactoferrin specificity relayed to a milder clinical picture." (PMID 34440897, 2021). "Neutrophil extracellular traps (NETs) from patients with systemic lupus erythematosus (SLE) are characterized by lower ubiquitylation and myeloperoxidase (MPO) as a substrate." (PMID 33176801, 2020).
systemic lupus erythematosus (continued). "In addition, p-ANCA can be directed against antigens other than MPO and is observed in a variety of autoimmune disorders including rheumatoid arthritis (RA), systemic lupus erythematosus (SLE), Sjogren’s syndrome (SS), polymyositis (PM) and dermatomyositis (DM)." (PMID 30764870, 2019). "Antibodies to thyroid microsomal and myeloperoxidase (MPO) are associated with graves’ disease and thyroiditis, antinuclear antibodies (ANA) and rheumatoid factor(RF) represent a serology hallmark in the diagnosis of systemic autoimmune rheumatic disease (SARD) such as systemic lupus erythematosus." (PMID 24606591, 2014). "More intriguingly, expression of DTA or loss of IRF4 in activated B-1 cells resulted in the production of IgG against protein autoantigens that are less specific for lupus including C1q, collagen, laminin, Gp2, PR3, and MPO." (PMID 41445737, 2025). "At this point, it should be added that MPO-ANCA, which is so important for the pathogenesis of AAV, has also been found in other autoimmune diseases, including systemic lupus erythematosus (SLE) and Sjögren’s syndrome (SS)." (PMID 40649843, 2025). "The diagnosis of AAV involves a comprehensive approach that includes clinical manifestations, serologic testing [immunoassays for PR3‐ANCAs and MPO-ANCAs, eosinophils, exclusion of anti–glomerular basement membrane disease and systemic lupus erythematosus (SLE)] and when feasible tissue biopsy." (PMID 37947275, 2024). "NETs, which was visualized as web-like or granular structures co-staining with MPO, histone H2A, and DAPI, were observed in kidney biopsies from lupus patients." (PMID 35686129, 2022). "A clue to this entity is the serologic profile which often includes other antibodies often seen in systemic lupus erythematosus (which hydralazine can also induce) in addition to ANCA (usually p-ANCA, MPO)." (PMID 33620515, 2021). "VH4-34 gene usage has been shown to be obligatory for the production of most pathogenic IgM cold-agglutinins and has been for demonstrated in IgM-RhF, IgG anti-dsDNA antibodies in systemic lupus erythematosus (SLE), and IgM anti-myeloperoxidase antibodies in systemic vasculitis." (PMID 25222933, 2014). "The absence of these typical lupus features, in the context of new MPO‐ANCA positivity, made MPA the more plausible diagnosis." (PMID 41403984, 2025). "Several studies have highlighted that MPO‐ANCA positivity in patients with SLE strongly correlates with the presence of an overlapping vasculitic syndrome rather than atypical lupus activity, with reported overlap rates between 5% and 10%." (PMID 41403984, 2025). "The presence of MPO‐ANCA positivity in a patient with background SLE raised the possibility of an overlapping vasculitis process rather than a lupus flare." (PMID 41403984, 2025). "The cooccurrence of systemic lupus erythematosus (SLE) and AAV reported in cases suggests that these two diseases may have shared genetic factors, especially in MPO-ANCA-positive AAV." (PMID 34820172, 2021). "Furthermore, with DC stimulated with ubiquitylated MPO a trend towards increased expression of CD25 and Ki67 was found in lupus CD4+ lymphocytes, while the opposite was documented in controls (p < 0.05)." (PMID 33176801, 2020). "Among all silica-exposed mice, B6 had significantly lower levels of BALF autoAb than other strains, including less anti-DNA IgM than silica-exposed mice in each of the lupus strains, less anti-DNA IgG than silica-exposed MRL and BXSB, and less anti-MPO than exposed BXSB." (PMID 31632407, 2019). "None of sera from patients with PTU-induced lupus could recognize the recombinant fragments of MPO, except that only one could recognize L chain." (PMID 24252385, 2013). "Perinuclear MPO-ANCA is a good serological marker for MPA, but it can also be found in patients with systemic lupus erythematosus (SLE), rheumatoid arthritis, drug-induced vasculitides (DIV), etc." (PMID 16207324, 2005).
systemic lupus erythematosus (continued). "Furthermore, myeloperoxidase and PADI4 deletion did not inhibit induced lupus." (PMID 32243431, 2020).
rheumatoid arthritis (60 papers, 2012 to 2026). A chronic, systemic autoimmune disorder characterized by inflammation in the synovial membranes and articular surfaces. "Several tissue lesions and the pathogenesis of diseases such as rheumatoid arthritis, cardiovascular and liver diseases, diabetes and cancer are linked to MPO-derived HOCl." (PMID 36142645, 2022). "Past studies have shown that MPO is an active disease biomarker associated with a variety of diseases, such as cardiovascular disease, cancer, kidney disease, lung injury, rheumatoid arthritis, and multiple sclerosis." (PMID 34880852, 2021). "The myeloid lineage-specific myeloperoxidase (MPO) is an essential component of the innate immune system associated with many pathologies including cardiovascular diseases, rheumatoid arthritis and multiple sclerosis." (PMID 33273015, 2021). "Elevated levels of NET components have been observed in peripheral blood, synovial fluids, rheumatoid nodules, and skin of patients with RA, with MPO-DNA complex levels positively correlated with ACPA concentrations." (PMID 38672433, 2024). "After injection of CFA, MPO a marker of neutrophil infiltration, which also plays a role in oxidative impairment in rheumatoid arthritis, was significantly elevated in joint tissues." (PMID 37520245, 2023). "The NET-protein MPO was found elevated in RA synovial fluid (SF), skin and rheumatoid nodules, indicating that NETs are present in these inflamed areas (joint/synovium)." (PMID 32276504, 2020). "Anti-MPO-positive patients were more likely to have an overlap syndrome with rheumatoid arthritis (15.4% vs 1.9%, p = 0.028)." (PMID 30764870, 2019). "The aim of this study was to determine the variations of hepatic proteins, myeloperoxidase, and iron in rheumatoid arthritis Tunisian patients and their implications in inflammation and in iron metabolism." (PMID 28894708, 2017). "Ca-gluconate has been shown to reduce expression of pro-inflammatory cytokines IL-6 and TNF-α, as well as myeloperoxidase levels in both burn and rheumatoid arthritis mouse models." (PMID 28604843, 2017). "The strongest myeloperoxidase staining was also detected in the precipitate fraction of the necrotic inner mass of the rheumatoid nodule." (PMID 27765067, 2016). "The expression of the enzyme myeloperoxidase (MPO) was selected as an inflammatory marker due to evidence supporting MPO as a reliable inflammatory marker in a range of pathogenesis including cancer, rheumatoid arthritis and cardiovascular disease in addition to tissue injury." (PMID 32716937, 2020). "This might be an explanation of the enhanced LPC contents in joint fluids in patients with rheumatoid arthritis, which are also characterized by elevated MPO activities." (PMID 28090245, 2016). "Moreover, it is recently shown that in patients with active rheumatoid arthritis a very high concentration of MPO can be detected and it positively correlates with IgM levels." (PMID 25524130, 2015). "Elevated MPO levels have been observed in several inflammatory diseases including rheumatoid arthritis (RA)." (PMID 29669993, 2018). "We aimed to assess hepatic proteins in rheumatoid arthritis patient’s: inflammation markers (high-sensitive C-reactive protein (CRPhs), haptoglobin (Hp)), and those implicated in iron metabolism (ferritin, Albumin (Alb), Cp, α-1-acid glycoprotein (AAG) and Tf) and MPO." (PMID 28894708, 2017). "Patients with rheumatoid arthritis and giant cell arteritis showed a variable proportion of neutrophils with adherent platelets, with an inverse correlation between the percentage of platelet-neutrophil heterotypic aggregates and the neutrophil MPO content (r = 0.59, P<0.01)." (PMID 22761804, 2012). "In rheumatoid arthritis (RA), NETosis-derived components—including extracellular DNA, histones, and myeloperoxidase (MPO)—together with lipid oxidation products such as oxidised LDL, synergistically amplify inflammatory responses and drive synovial membrane destruction." (PMID 41465350, 2025).